CNGA3 (cyclic nucleotide gated channel subunit alpha 3)
Diseases named in the same sentence as CNGA3 in open-access papers (continued):
Sharing a sentence is not in itself a finding about the gene and the disease.
achromatopsia (continued). "Theoretically, the last exon (sixth exon) of the Cnga3 gene contributes most of the CNGA3 protein that forms the CNG channel; thus, placing a “floxed-STOP” cassette in front of the sixth exon is the ideal choice to create a reversible mouse model of achromatopsia." (PMID 34360834, 2021). "A naturally occurring, non-human primate (NHP) model of achromatopsia with a homozygous mutation in the PDE6C gene had phenotypic similarities to that of the human achromatopsia patients and was used to understand the cone-mediated visual loss associated with CNGA3/B3 mutations." (PMID 32967234, 2020).
cone-rod dystrophy (8 papers, 2008 to 2024). Inherited retinal dystrophies that belong to the group of pigmentary retinopathies. "The best example is a novel missense variant (p.C319R) in CNGA3 identified by whole-exome sequencing in a family with cone-rod dystrophy (CRD)." (PMID 32967234, 2020). "In addition, differential diagnosis may be made between ACHM and other CNGA3-associated retinopathy, such as cone dystrophy or cone-rod dystrophy (CORD), Leber congenital amaurosis (LCA), and oligocone trichromacy (OCT)." (PMID 39678380, 2024). "Mutations in the CNGA3 gene are recognized as the most common causes of ACHM and cone-rod dystrophies in the Chinese population." (PMID 26493561, 2015). "Mutations in CNGA3 are considered the most common cause of ACHM and cone-rod dystrophies (CORDs) in Chinese, in which only cone photoreceptors are usually affected, although CNGA3 mutations have been reported in a patient with CORDs and Leber congenital amaurosis (LCA)." (PMID 26493561, 2015). "The genes involved in cone degeneration, CNGB3, CNGA3 and GNAT2, and the genes involved in cone-rod dystrophy, ABCA4, RDH5, Cord8, Cord9, RPGRIP1, GUCY2D and CRX, were all excluded from being involved in the cone-rod dystrophy described in this family of SWHD." (PMID 18593457, 2008). "Three of the genes, CNGB3, CNGA3 and GNAT2, involved in cone degeneration and seven genes and loci, ABCA4, RDH5, CORD8, CORD9, RPGRIP1, GUCY2D and CRX, reported to be involved in cone-rod dystrophies were studied." (PMID 18593457, 2008).
achromatopsia 2 (5 papers, 2015 to 2024). Achromatopsia 2 is a condition that affects the color vision. "We report the results of the first, to our knowledge, human clinical study that evaluated gene therapy for type 2 achromatopsia, an inherited retinal disorder caused by variants in CNGA3 and leading to cone photoreceptor dysfunction." (PMID 32352493, 2020). "Achromatopsia type 2 (ACHM2) is a severe, inherited eye disease caused by mutations in the CNGA3 gene encoding the α subunit of the cone photoreceptor cyclic nucleotide-gated (CNG) channel." (PMID 28596720, 2017). "The Cnga3-/- line is a model of achromatopsia type 2 and particularly specific in the removal of any light-activated cone signalling, while the rod system stays functionally intact." (PMID 26807953, 2016).
cone dystrophy (5 papers, 2010 to 2024). An inherited ocular disorder characterized by the loss of cone cells, the photoreceptors responsible for both central and color vision. "Insights from our study will facilitate counseling regarding the molecular and phenotypic landscape of CNGA3-related cone dystrophies." (PMID 35456423, 2022). "This region contains the CNGA3 gene, which has previously been implicated in ACHM and cone dystrophy." (PMID 20454696, 2010). "Mutations in CNGA3, CNGB3, and PDE6C have also been associated with cone dystrophy in a small proportion of patients." (PMID 20454696, 2010).
Leber congenital amaurosis (5 papers, 2015 to 2024). Leber congenital amaurosis (LCA) is a retinal dystrophy defined by blindness and responses to electrophysiological stimulation (Ganzfeld electroretinogram (ERG)) below threshold, associated with severe visual impairment within the first year of life. "This modality of treatment has shown efficacy in clinical trials treating RPE65-associated Leber congenital amaurosis (LCA), CHM-associated choroideremia, CNGA3-related achromatopsia, and MERTK-associated retinitis pigmentosa." (PMID 36012955, 2022).
myopia (4 papers, 2018 to 2025). "Hyperopia and myopia were equally frequent among patients presenting CNGA3 mutations (50% and 50%, respectively), while myopia was more frequent than hyperopia among subjects with CNGB3 mutations (86% versus 14%)." (PMID 29618791, 2018).
Photophobia (4 papers, 2022 to 2025). Excessive sensitivity to light with the sensation of discomfort or pain in the eyes due to exposure to bright light. "Members of Family 1 were also found to have CNGA3 c.955T > C; p.Cys319Arg mutations associated with comparable phenotypes, including nystagmus, photophobia, and reduced visual acuity." (PMID 40737315, 2025). "Mutations in CNGA3 impair the light-sensing function of cone cells, leading to color blindness, solar blindness, poor vision and photophobia." (PMID 38789412, 2024). "Clinical findings of the presented patients include outer nuclear layer thinning with or without macular atrophy, myopic fundus, nystagmus, and photophobia highlighting the role of CNGA3 in normal vision." (PMID 35456423, 2022).
retinal degeneration (3 papers, 2013 to 2021). Degeneration of the retina. "A cross-sectional analysis of the largest patient cohort to date suggests that biallelic variants in CNGA3 and CNGB3 in most patients result in slow retinal degeneration that occurs over decades of life." (PMID 34449556, 2021). "Down-regulation of genes in the cone phototransduction pathway has been reported in different mouse models of retinal degeneration, including Cnga3−/−/Nrl−/− (cone-enriched) mice, in which photoreceptors are incapable of light-induced hyperpolarization." (PMID 29179637, 2018).
retinal diseases (3 papers, 2019 to 2025). "Additionally, while 661W cells express several photoreceptor markers, they do not express all the genes or proteins found in mature photoreceptors, particularly those involved in specific retinal diseases, such as CNGA3 and RPE65." (PMID 40170180, 2025). "The CNGA3, CACNA1F, and RPGRIP1 genes are the most well-known from our list, and this article discusses their photoreceptor function and implications in retinal diseases." (PMID 40737315, 2025).
Nystagmus (2 papers, 2022 to 2025). Rhythmic, involuntary oscillations of one or both eyes related to abnormality in fixation, conjugate gaze, or vestibular mechanisms. "Among CNGA3 associated spectrum of inherited cone disorders, ACHM accounts for 20–30% cases and is characterized by vision impairment, partial or complete color blindness, nystagmus, and photo dysphoria especially during daytime." (PMID 35456423, 2022).
retinitis pigmentosa (2 papers, 2022 to 2025). Retinitis pigmentosa (RP) is an inherited retinal dystrophy leading to progressive loss of the photoreceptors and retinal pigment epithelium and resulting in blindness usually after several decades. "The resulting dendrogram captures some of the known phenotypic similarities in IRDs such as Stargardt phenocopy genes (ABCA4, PRHP2 and PROM1), retinitis pigmentosa genes (RPGR and USH2A) and achromatopsia genes (CNGA3 and CNGB3)." (PMID 40567353, 2025).
anorexia nervosa (1 paper, 2018). A disorder most often seen in adolescent females characterized by a refusal to maintain a minimally normal body weight, an intense fear of gaining weight, a disturbance in body image, and, in postmenarcheal females, the development of amenorrhea. "According to the KEGG Database, CNGA3 is in a common pathway, i.e. olfactory transduction (KEGG ID hsa04740), with CALM1, a candidate gene for anorexia nervosa." (PMID 30415424, 2018).
Channelopathies (1 paper, 2015). "Here, we report the first canine models for CNGA3-associated channelopathy caused by R424W or V644del mutations in the canine CNGA3 ortholog that accurately mimic the clinical and molecular features of human CNGA3-associated ACHM." (PMID 26407004, 2015). "The R424W and V644del mutations in CNGA3 represent the first canine models of ACHM2-associated channelopathies." (PMID 26407004, 2015).
diabetic (1 paper, 2024). "Upstream regulator analysis suggested COMMD1, HIF1A, EGLN, PIK3R1 and MTORC1 as major upstream regulators for the phase shifts, while HSP90B1, YWHAZ, CNGA3, COL2A1 and TFRC were identified as the major upstream regulators for the amplitude changes observed in the diabetic retina." (PMID 38039846, 2024).
glioblastoma (1 paper, 2023). The most malignant astrocytic tumor (WHO grade IV). "By contrast, when the authors examined gene expression patterns in the Ivy Glioblastoma Atlas Project (Ivy GAP) database, and considered expression restricted to the central solid tumor region, high CNGA3 was associated with increased, rather than decreased, survival." (PMID 37100462, 2023).
retinopathy (6 papers, 2020 to 2025). "An accessory CNGA3 variant with the two CNGB3 variants, one being c.1208G > A;p.(R403Q), was recently described as exacerbating CNG-channel retinopathy." (PMID 36980963, 2023). "The cross-sectional analysis showed evidence that CNGA3/CNGB3 retinopathy is a progressive disease that follows four OCT stages; (I) preserved ISe, (II) disrupted ISe, (III) ISe loss, and (IV) ISe, and RPE loss, which occur slowly over decades." (PMID 34449556, 2021). "Animal models support the proposed degenerative nature of CNGA3/CNGB3 retinopathy." (PMID 34449556, 2021).
cancer (2 papers, 2021 to 2024). A tumor composed of atypical neoplastic, often pleomorphic cells that invade other tissues. "In addition, we also identified 6 upregulated genes not typically associated with cancer (ARC, C1orf167, CNGA3, KRT75, SPRR1B, STUM)." (PMID 38038766, 2024).
CNGA3 also shares sentences with these, for which no sentence is quoted: Retinal dystrophy (3 papers); Blindness (2); choroideremia (2); Hypermetropia (2); achromatopsia 3 (1); blue cone monochromacy (1); Bornholm eye disease (1); Chorioretinal atrophy (1); complete achromatopsia (1); congenital nystagmus (1); congenital stationary night blindness (1); epilepsy (1); genetic disease (1); geographic atrophy (1); glaucoma (1); glioma (1); insomnia (1); macular degeneration (1); nemaline myopathy 2 (1); occult macular dystrophy (1); ocular albinism (1); oculocutaneous albinism (1); Progressive cone dystrophy (1); retinal (1); tumor (1).